STAG2 (STAG2 cohesin complex component)
Diseases named in the same sentence as STAG2 in open-access papers (continued):
Sharing a sentence is not in itself a finding about the gene and the disease.
leukemia (21 papers, 2016 to 2025). A malignant (clonal) hematologic disorder, involving hematopoietic stem cells and characterized by the presence of primitive or atypical myeloid or lymphoid cells in the bone marrow and the blood. "In HiChIP experiments, the authors find that STAG2 loss confers decreased chromatin looping associated with loci encoding leukemia drivers." (PMID 35902807, 2022). "Among the metabolic genes downregulated in NPM1/cohesin-mut compared with NPM1-mut AML, CHST13, ADCY9, PRR16, LPL, and SLC1A3 were confirmed by STAG2-deficient model of NPM1-mut leukemia." (PMID 34193978, 2021). "We found that STAG2 mutation in K562 leukemia cells increased chromatin accessibility at BRD4 binding sites at the RUNX1 and ERG genes." (PMID 34202641, 2021). "In a mouse model of leukemia, Stag2 mutation seems to affect genes involved in hematopoietic stem cell renewal and differentiation." (PMID 31898537, 2020). "Collectively, these experiments identify STAG1 as a vulnerability of STAG2 mutated cells in engineered solid cancer and leukemia models." (PMID 28691904, 2017). "However, loss of STAG2 alone is insufficient for the development of leukemia, and STAG2/Runx1, STAG2/IDH1, and other combinations are frequent." (PMID 39594644, 2024). "In summary, we identified specific signaling pathways by which co-operative mutations in GATA1 and STAG2 may develop leukemia in a trisomy background." (PMID 35203280, 2022). "Interestingly there is evidence from several studies regarding compensatory STAG1 activity in STAG2-deficient leukemia, which might result in altered cohesin processivity and a shift from smaller chromatin domains to larger domains." (PMID 35902807, 2022). "The presence of STAG2, SRSF2 and RUNX1 mutations, alone or in combination, shortening both the time to leukemia transformation and the OS within MDS patients with isolated +8." (PMID 37568638, 2023). "Another CN-LOH region of interest was identified in sample S5, showing CN-LOH of Xq25–qter, involving four genes (STAG2, BCORL1, PHF6, and BRCC3) that have previously been implicated in different types of leukemias." (PMID 36831635, 2023). "CD117/KIT expression is a marker of GATA1s-induced pre-leukemia- and GATA1s/STAG2-knock-out-induced leukemia-initiating cells." (PMID 36035173, 2022). "Finally, in order to examine whether response to PARP inhibition in primary human leukemia cells is STAG2 mutation dependent, we treated STAG2-mutant and WT primary AML patient samples with talazoparib and noted a dose- and genotype-dependent sensitivity to the drug." (PMID 33351783, 2021). "Upregulation of HOXA genes with concomitant decrease in H3K27me3 and increase in activating H3K27ac was also observed in STAG2 mutant OCI-AML3 leukemia cells." (PMID 34202641, 2021). "We show that sensitivity to GSK3 inhibition is likely due to stabilization of β-catenin in cohesin-mutant cells, and that Wnt-responsive gene expression is highly sensitized in STAG2-mutant CMK leukemia cells." (PMID 33284104, 2020). "Thus, GATA1s-mediated activation of toll-like receptor signaling likely leads to myeloid commitment, while the STAG2 knockout halts myeloid differentiation and promotes self-renewal leading to leukemia." (PMID 35203280, 2022). "Wnt-responsive transcription was also greatly sensitized in STAG2 mutant leukemia cells." (PMID 34202641, 2021). "For instance, all cases with mutated STAG2 had another CS-mutation in the original report defining CS-AML, suggesting that co-existence of multiple driver mutations plays a crucial role in the development of this type of leukemia." (PMID 33799787, 2021). "The altered genomic architecture also resulted in altered MAPK signalling and sensitivity to MEK inhibition which may be a therapeutic strategy for the treatment of STAG2 mutant leukaemia." (PMID 32883299, 2020).
leukemia (continued). "In the background of STAG2 absence, additional STAG1 loss abrogated hematopoiesis, consistent with the reported synthetic lethality between STAG1 and STAG2 in leukemia cell lines and the redundancy in STAG1 and STAG2 function in chromatid segregation." (PMID 33799787, 2021).
acute myeloid leukemia (20 papers, 2014 to 2026). Acute myeloid leukemia (AML) is a group of neoplasms arising from precursor cells committed to the myeloid cell-line differentiation. "In acute myeloid leukemia, STAG2 knock out (KO) or loss-of-function mutation sensitizes cancer cells to treatment with the PARP inhibitor talazoparib." (PMID 40025053, 2025). "Moreover, a euploid karyotype common in acute myeloid leukemia was also associated with loss-of-function mutations in STAG2." (PMID 35409298, 2022). "Notably, a STAG2 mutation was identified as a driver of clonal evolution from myeloid dysplastic syndrome to secondary acute myeloid leukemia." (PMID 24484537, 2014). "The exploration of how STAG2 mutations affect the transcriptome and epigenome was expanded to acute myeloid leukemia (AML)." (PMID 39594644, 2024). "STAG2 mutations are mostly nonsense, frameshift, and splice mutants found in melanoma, acute myeloid leukemia (AML), Ewing’s sarcoma, and myelodysplastic syndrome (MDS)." (PMID 36612210, 2022). "Mutations in the cohesin complex components (STAG2, RAD21, SMC1A, SMC3, and PDS5B) are recurrent genetic drivers in myelodysplastic neoplasm (MDS) and acute myeloid leukemia (AML)." (PMID 39033241, 2024). "The genetics of cohesinopathy provide evidence for RAD21, STAG2, SMC1A, and SMC3 as driver mutations in acute myeloid leukemia (AML), chronic myeloid leukemia (CML), and pre-leukemic states (myelodysplastic syndrome; MDS)." (PMID 35902807, 2022). "In some forms of acute myeloid leukemia (AML), the cumulative level of mutations in RAD21, SMC1a, SMC3, and STAG2 genes reaches 13%." (PMID 35353576, 2022). "We developed models of cohesin-mutant myelodysplastic syndromes and acute myeloid leukemia and demonstrated a shift from STAG2- to STAG1-cohesin complexes, increased DNA damage, and sensitivity to PARP inhibition." (PMID 33351783, 2021). "Mutations in members of the cohesin complex are known early drivers of myelodysplastic syndromes (MDS) and acute myeloid leukaemia (AML), with STAG2 the most frequently mutated complex member." (PMID 32883299, 2020). "Mutations present in STAG2, SMC3, RAD21 and SMC1A were also described in acute myeloid leukemia." (PMID 35409298, 2022). "For example, somatic mutations in the eight genes that comprise the cohesin ring (SMC1A, SMC3, STAG1, STAG2, RAD21) and the cohesin-ring support genes (NIPBL, MAU2, WAPL, PDS5A, PDS5B) and CTCF are frequently found in many cancer types and are especially common in acute myeloid leukemia (AML)." (PMID 36171609, 2022).
melanoma (15 papers, 2013 to 2025). A malignant, usually aggressive tumor composed of atypical, neoplastic melanocytes. "Mutational inactivation of STAG2 is a major cause of the resistance of BRAF-mutant melanomas to BRAF/MEK inhibitors." (PMID 37479689, 2023). "There is evidence supporting that mutational inactivation of STAG2 is a major cause of the resistance of BRAF-mutant melanomas to BRAF/MEK inhibitors." (PMID 37479689, 2023). "However, the difference between BRAF-mutated melanomas and thyroid cancers on STAG2 inactivation-induced resistance mechanism still need to be further investigated." (PMID 37479689, 2023). "In contrast, STAG2 or STAG3 mutation in melanoma conferred resistance to BRAF inhibition owing to reactivation of MEK-MAPK (ERK) signaling, which suggests that in a melanoma context, STAG2 mutation status could inform therapeutics." (PMID 34202641, 2021). "Here we show that depletion of STAG2 in melanoma cells leads to expansion of topologically associating domains (TADs) and enhances the formation of acetylated histone H3 lysine 27 (H3K27ac)-associated DNA loops at sites where binding of STAG2 is switched to its paralog STAG1." (PMID 35388001, 2022). "However, the potential tumor suppressor function of STAG2 in melanoma and the underlying mechanism remains unclear." (PMID 35388001, 2022). "However, our in-depth analysis on the TAD boundaries reveal that the switch of STAG2 to STAG1 at the TAD boundaries could be actually associated with the expansion of TADs upon STAG2 knockdown in melanoma cells." (PMID 35388001, 2022). "Collectively, these results indicate that, although STAG2 knockdown activates ERK signaling in both BRAF-mutant thyroid cancer cells and melanoma cells, it causes distinct cellular response to MEK inhibitor." (PMID 37479689, 2023). "H3K27ac HiChIP analyses identified interferon regulatory factor 9 (IRF9) as a major direct target of stromal antigen 2 (STAG2) in melanoma cells." (PMID 36768307, 2023). "We further identify Interferon Regulatory Factor 9 (IRF9) as a major direct target of STAG2 in melanoma cells via integrated RNA-seq, STAG2 ChIP-seq and H3K27ac HiChIP analyses." (PMID 35388001, 2022). "Here, we show that IRF9, a key component in the type I interferon signaling pathway, is a direct target of STAG2 in melanoma through integrated analyses of RNA-Seq, ChIP-seq, and H3K27ac HiChIP." (PMID 35388001, 2022). "Loss of STAG2 in melanoma results in IRF9 activation, which in turn upregulates PD-L1 expression in cancer cells, suggesting a potential tumor suppressor function of STAG2 in immune evasion." (PMID 35388001, 2022). "We confirmed knockdown of STAG2 increased levels of IRF9 expression in multiple melanoma cell lines." (PMID 35388001, 2022). "We found that knockdown of STAG2 increased both mRNA and protein levels, as well as the surface expression of PD-L1 in melanoma cells." (PMID 35388001, 2022). "Since IFN signaling and IRF9 in particular play critical roles in regulating the expression of PD-L1 in cancer cells, we examined whether STAG2 modulates the expression of PD-L1 in melanoma cells." (PMID 35388001, 2022). "Lastly, our identification of IRF9 as a key target of STAG2 in the context of 3D genome organization in melanoma cells raises the possibility that upregulation of type I interferon signaling may contribute to the tumor suppressor function of STAG2." (PMID 35388001, 2022). "We focused on characterizing IRF9 as a direct target of STAG2 in melanoma cells, because that IRF9 is a central transcription factor in type I interferon signaling pathway and that motifs of several IRF family members were found to be enriched in the enhanced H3K27ac loop anchors." (PMID 35388001, 2022). "Moreover, it has been recently reported that STAG2 inactivation confers resistance to BRAF inhibitors in melanoma." (PMID 28430577, 2017).
melanoma (continued). "In a later work based on IHC of melanoma specimens, it was found that DUSP6 protein, as well as STAG2 and STAG3, two cohesin complex components, are decreased following treatment with BRAF or MEK (dabrafenib, trametinib, andvemurafenib) inhibitors." (PMID 40943262, 2025). "To characterize the role of STAG2 in 3D genome organization in melanoma cells, we carried out ChIP-seq against STAG2, STAG1, SMC1A, and CTCF as well as Hi-C analyses in M14 melanoma cells stably expressing inducible shRNA of STAG26." (PMID 35388001, 2022). "Consistently, melanoma cell lines (A375, Mel1617, WM902, WM983, and M14) resistant to BRAFi or MEKi showed reduced expression of STAG2 and STAG3, and their KD led to a further decrease of DUSP6 as well as of BRAFi sensitivity, along with an increase in ERK1/2 phosphorylation." (PMID 40943262, 2025). "Unlike BRAF-mutant melanoma cells, STAG2 knockdown in BRAF-mutant thyroid cancer cells did not affect their cellular response to MEK inhibitor." (PMID 37479689, 2023). "Considering that knocking down STAG2 in BRAF-mutant melanoma cells significantly decreased their sensitivity to BRAF/MEK inhibitors, we thus attempted to determine whether STAG2 knockdown affected the response of BRAF-mutant thyroid cancer cells to BRAF/MEK inhibitors." (PMID 37479689, 2023). "In addition, unlike melanoma, STAG2 knockdown also did not affect the sensitivity of these cells to MEK inhibitor." (PMID 37479689, 2023). "Knockdown of STAG2 in melanoma cells did not apparently affect cell cycle progression, apoptosis, or growth of xenograft tumors in nude mice, but significantly decreased the sensitivities of melanoma cells to inhibition of BRAF and/or MEK in both culture cells and xenograft mouse models." (PMID 35388001, 2022).
myelodysplastic syndrome (15 papers, 2019 to 2026). A clonal hematopoietic disorder characterized by dysplasia and ineffective hematopoiesis in one or more of the hematopoietic cell lines. "Mutations in STAG2, a member of the Cohesin complex, occur in myelodysplastic syndromes (MDS) and acute myeloid leukaemia (AML)." (PMID 32883299, 2020). "A recent research has shown that Stag2 and Runx1 play an important role in regulating chromatin looping and transcription in hematopoiesis, and cohesin-Runx1 deficiency can induce myeloid-skewed expansion of HPSCs and myelodysplastic syndromes (MDS)." (PMID 33928020, 2021). "In addition, mutations in the core cohesion complex gene STAG2 (Stromal Antigen 2) induce DNA damage, stalled replication forks and a high genetic dependency on PARP1 in AML/myelodysplastic syndrome (MDS) cells." (PMID 36497275, 2022). "In myelodysplastic syndromes (MDS), a heterogeneous group of clonal hematopoietic disorders characterized by cytopenia, ineffective hematopoiesis and an increased risk of progression to AML, RAD21, STAG2, and SMC1A are the most frequently mutated genes (∼15%) and are associated with poor survival." (PMID 30873408, 2019). "In these updated definitions, mutations of the cohesin subunit SA-2 (STAG2) are recognized as a defining alteration of AML with myelodysplasia-related gene mutations (in absence of other defining alterations) irrespective of prior presence of myelodysplastic neoplasms." (PMID 36693840, 2023).
myeloid neoplasm (14 papers, 2015 to 2026). Proliferation of myeloid cells originating from a primitive stem cell. "The cohesin complex, comprising SMC1, SMC3, RAD21, and either STAG1 or STAG2, is a recurrent mutational target, with STAG2 (stromal antigen 2) mutations accounting for more than half of cohesin mutations in myeloid malignancies." (PMID 40565579, 2025). "Cohesin subunit STAG2 is frequently mutated in myeloid malignancies, but the individual contributions of Stag variants to haematopoiesis or malignancy are not fully understood." (PMID 33365313, 2020). "Mutations in cohesin subunits RAD21, SMC1, SMC3, and STAG2 are seen in several myeloid neoplasms." (PMID 39747661, 2025). "ASXL1mt in myeloid neoplasms were considered to be ubiquitously accompanied by mutations of RUNX1, SRSF2, STAG2, NRAS, or IDH2, in addition to wild‐type NPM1 and FLT3,14, 21, 22, 28 which was aligned with the mutation profile in our cohort." (PMID 38146893, 2023). "STAG2 mutations are almost always accompanied by other driver mutations, such as in RUNX1, SRSF2, and ASXL1, but how cohesin mutations induce myeloid neoplasms in conjunction with other driver mutations remains to be determined." (PMID 33799787, 2021). "Moreover, recent studies have shown the interaction of RUNX1 with other frequently co-mutated drivers, such as STAG2 and ASXL1, thus promoting the advancement of myeloid neoplasms." (PMID 33799787, 2021). "Recurrent mutations and deletions involving multiple components of the mitotic cohesion complex, including STAG2, RAD21, SMC1A and SMC3, were reported in different myeloid neoplasms." (PMID 26317787, 2015). "Patients with cohesin-mutant myeloid malignancies never present with complete, biallelic inactivation of any cohesin subunit, with the notable exception of STAG2, which has a paralog, STAG1." (PMID 33351783, 2021).
Myelodysplasia (11 papers, 2022 to 2025). Clonal hematopoietic stem cell disorders characterized by dysplasia (ineffective production) in one or more hematopoietic cell lineages, leading to anemia and cytopenia. "In particular, the adverse-risk group has been expanded to include seven additional mutations: BCOR, EZH2, SF3B1, SRSF2, STAG2, U2AF1, and ZRSR2—together with ASXL1 and RUNX1 (already included in ELN 2017)—forming the “myelodysplasia-related” (MR) gene group." (PMID 41464583, 2025). "The presence of mutations in at least one gene associated with myelodysplasia (i.e., SRSF2, SF3B1, U2AF1, ZRSR2, ASXL1, EZH2, BCOR, or STAG2) was significantly more frequent in older patients." (PMID 35805006, 2022). "Mutated STAG2 (cohesin complex): Mutations in the cohesin subunit SA-2 (STAG2) define AML with myelodysplasia-related gene mutations, irrespective of prior MDS, and are considered a marker of poor prognosis." (PMID 38673842, 2024). "Seventy-nine patients, or 45% of all re-classified patients, were moved from ELN-2017 favorable (n = 11) or intermediate (n = 68) to ELN-2022 adverse risk based on the inclusion of additional myelodysplasia-related (MR) mutations (BCOR, EZH2, SF3B1, SRSF2, STAG2, U2AF1, ZRSR2) as poor-risk markers." (PMID 37041198, 2023).
virus infection (7 papers, 2008 to 2025). "We hypothesized that the observed IFN activation mediates broad resistance to virus infection in STAG2-deficient cells." (PMID 29662124, 2018). "In rotavirus, STAG2 deficiency induces IFN responses via the cGAS-STING pathway, ultimately restricting viral infection." (PMID 40981223, 2025). "STAG2 has been observed to play a central role in viral infection, including rotavirus and porcine deltacoronavirus." (PMID 40981223, 2025). "A novel role of STAG2 as a crucial component of the innate immune response was reported, suggesting STAG2 deficiency induces interferon responses via cGAS-STING pathway and restricts virus infection." (PMID 36016405, 2022). "While no studies appear to draw a clear link between hsa-miR-140-3p and STAG2 expression, especially in the context of viral infection, it is likely that there is a direct correlation between these, which could be a target of future research." (PMID 40981223, 2025). "STAG2 is proven to be involved with viral infection via STING signaling." (PMID 36653483, 2023). "After this screening, four genes (STAG2, CD40LG, SMARCA2 and OLFML3) were found to have predictively high scores from the databases and their established links to the immune response and viral infection." (PMID 40981223, 2025). "Furthermore, the identification of STAG2 and SMARCA2 was further highlighted by their role in other viral infections." (PMID 40981223, 2025). "From this, it can be seen that STAG2 and SMARCA2, while both being regulated by the same miRNA, potentially have directly contrasting roles, with one being antiviral (SMARCA2) and the other supporting viral infection (STAG2)." (PMID 40981223, 2025). "STAG2, an enhancer of TNF production, and the member of the MAPK pathway, ATF2, a transcription activator of both IFN-β and TNF-α in response to virus infection, were downregulated." (PMID 18796724, 2008).
breast carcinoma (6 papers, 2014 to 2024). "To understand the functional relevance of such variations in non-coding regions we assessed their association with gene expression and patients’ outcome and demonstrated that the transcriptomic signature of STAG2 gene was associated with good prognosis in ER-positive/HER2-negative breast cancer." (PMID 29559730, 2018).
colon carcinoma (6 papers, 2017 to 2023). "To further examine this fascinating phenotype, we first validated the screen results by knocking out STAG2 in Caco-2 and T84 cells, both human colonic cancer-derived epithelial cell lines." (PMID 29662124, 2018). "To identify factors whose inactivation would be synthetic lethal with loss of STAG2 function, we first used CRISPR/Cas9 to inactivate STAG2 in near-diploid, chromosomally stable HCT 116 colon carcinoma cells." (PMID 28691904, 2017).